CRYBB2P1 (crystallin beta B2 pseudogene 1)
Synonyms: formerly CRYB2B
Gene: Transcribed unprocessed pseudogene on chromosome 22 (25,455,712 to 25,459,681, forward strand). Ensembl gene ENSG00000100058.
Diseases named in the same sentence as CRYBB2P1 in open-access papers:
CRYBB2P1 is named in the same sentence as 4 diseases in open-access papers, as found by Europe PMC text mining. Sharing a sentence is not in itself a finding about the gene and the disease. The quoted sentences say what the papers report.
colorectal tumors (1 paper, 2014). "Higher expression of the probe for CRYBB2P1 has been detected in a number of tissues from African Americans, including breast (of mixed subtypes), prostate and colorectal tumors, disease-free breast and prostate tissues as well as blood endothelial cells." (PMID 24495414, 2014).
tumor (3 papers, 2021 to 2024). "Nevertheless, the documented association between CRYBB2 expression and multiple tumor types suggests that CRYBB2/CRYBB2P1 may serve as promising diagnostic or prognostic biomarkers in specific populations." (PMID 34118792, 2021). "Follow-up studies from CBCS found associations between higher expression of PSPH and risk of recurrence (HR 1.76, 95% CI 1.15–2.68) and that both CRYBB2 and CRYBB2P1 promote tumor progression in vivo." (PMID 36833598, 2023). "Although molecular evidence is still inconclusive, these findings suggested that differential expression of CRYBB2/CRYBB2P1 contribute to poor outcomes in African American women by impacting tumor cell proliferation, invasion, metastasis, and tumor immunity." (PMID 34118792, 2021).
malignant tumors (1 paper, 2021). "Notably, overexpression of either CRYBB2, the gene encoding for βB2-crystallin in humans, or its highly homologous pseudogene, CRYBB2P1, correlates with differential survival outcomes in African American patients with different malignant tumors." (PMID 34118792, 2021).
CRYBB2P1 also shares sentences with these, for which no sentence is quoted: breast carcinoma (1 paper).